CD80 (CD80 molecule)
Diseases named in the same sentence as CD80 in open-access papers (continued):
Sharing a sentence is not in itself a finding about the gene and the disease.
tumor (continued). "Altogether, our results suggest that CD38+ macrophages are associated with an M1 phenotype that is characterized by higher CD80 expression and a pro-inflammatory cytokine profile, all of which contribute to the anti-tumor immune response." (PMID 31552039, 2019). "Upregulating CD80 on tumor cells potentially can result in T cell exhaustion and augment tumor progression." (PMID 31112530, 2019). "While induction of PD-L1 on B-ALL target cells limited CD19xCD3-induced killing, CD80 up-regulation increased tumor cell sensitivity to CD19xCD3 in vitro." (PMID 31882897, 2019). "We selected the OPM-2 as the MM target in vivo since this tumor cell line lacks the expression of co-stimulatory molecules, while the other tumor cell lines retain the expression of either CD80 or CD86." (PMID 31040928, 2019). "This method has been used to deliver a combination of OX40L, CD80, and CD86 encoding mRNAs in different subcutaneous two-tumor models, where only one tumor was treated." (PMID 31878087, 2019). "Most tumors do not express CD80, but engineered expression of endogenous or exogenous CD80 on tumor cells has been shown to enhance antitumor T cell responses and promote tumor regression." (PMID 31112530, 2019). "DCs play key roles in the tumor-antigen presentation and the priming of effector T cells, and CD80 and CD86 are two markers of DC maturation and are critical for the activation of costimulatory signaling during DC priming of CD8+ T cells." (PMID 31771653, 2019). "mDCs able to present tumor antigens to T cells were confirmed by the presence of surface markers CD80, CD83, and CD86 and HLA-ABC and HLA-DR antigens." (PMID 31546936, 2019). "One of the most potent costimulatory molecules involved in the recognition and killing of tumor cells is CD80." (PMID 31072360, 2019). "We also performed immunofluorescence staining for M1 TAM activation markers‐CD80 and iNos and eat‐me receptor calreticulin on tumor cells." (PMID 31376208, 2019). "They show an activated immune phenotype (CD23+, CD27+, CD80+) and are capable of tumor-specific Ig production." (PMID 31167511, 2019). "Loss of PIK3CA or inhibition of its effector AKT increased the expression of MHC class I and CD80 on tumor cells." (PMID 31112530, 2019). "Macrophages, specifically the CD163+ ones, were predominantly found at the tumor invasive front, whereas CD80+ macrophages were almost exclusively located in the ANM, which suggests a predominant anti-inflammatory polarization of TAMs." (PMID 31481956, 2019). "Mouse CD80+PD-L1+ tumor cells similarly maintained IFNγ production by activated PD-1+ mouse T cells." (PMID 31001479, 2019). "Flow cytometric analysis revealed that ssRNA and dual-function vector treatment significantly increased the proportion of pDCs (CD317+CD11c+B220+) in tumor tissues and also enhanced the expression of CD80 and CD40 on pDCs, which suggest the activation of pDCs." (PMID 31849942, 2019). "The data suggest that the anti-PD-L1 peptides block PD-1/PD-L1 and CD80/PD-L1 interactions simultaneously, leading to enhanced anti-tumor activity of the T cells." (PMID 31640814, 2019). "Flow cytometry using an anti-PD-L1 antibody that recognized a non-CD80-dependent epitope revealed co-localization of PD-L1 and CD80 on the plasma membrane of human tumor cells." (PMID 31001479, 2019). "Although CD80 was highly expressed by macrophages at the tumor ANM (~74%), the majority of macrophages in intratumor regions lack the expression of this pro-inflammatory marker." (PMID 31481956, 2019). "Tumor-derived TGF-β suppresses CD80 and CD86 costimulatory molecule expression by DCs and promotes the development of a PD-L1-expressing immunosuppressive DC subset capable of inhibiting CD8+ T cell activity in a metastatic ovarian cancer model." (PMID 31921140, 2019).
tumor (continued). "CTLA-4 can trigger apoptosis in CTLA-4-expressing tumour cells after the cells interact with soluble CD80 or CD86 recombinant ligands, and the induction of apoptosis occurs through a caspase-8-dependent mechanism." (PMID 31506501, 2019). "The susceptibility of these tumors to immunosurveillance is due at least in part to increased expression of MHC I and CD80 on the tumor cell surface." (PMID 31112530, 2019). "In a study examining immunogenic effects of CDDP, Beyranvand and colleagues demonstrated that CDDP can enhance tumor cell death with the assistance of CTLs activated by CD80/86-mediated costimulation." (PMID 31450627, 2019). "In the tumor regions, CD80 staining is very low and, similarly to the other markers evaluated, its expression is higher in the IF than in the IT (0.12 vs. 0.04%)." (PMID 31481956, 2019). "The TAMs in the 3BD9 vaccinated mice maintained a high level of Ly6G expression throughout the tumor growth phase, and negligible levels of CD80 and PD-L1." (PMID 31882679, 2019). "CTLA-4 is structurally similar to CD28 and binds to CD80 (B7-1) / CD86 (B7-2) on APCs (or tumor cells) at a higher affinity than CD28, which suggests an interference with T cell activation." (PMID 29988281, 2018). "In another study, the CD80-Fc fusion protein gene was delivered to tumor cells in vivo in the context of an oncolytic replication-competent herpes simplex virus." (PMID 30482248, 2018). "In tumor of HT29 tumor-bearing mice, CD80-expressing-cells predominantly localized with tumor cells, and MRC1-expressing cells were also present at steady state." (PMID 29690614, 2018). "In the spleens of HT29 tumor-bearing mice, CD80-expressing cells were very few and MRC1-expressing cells were dominant at steady state." (PMID 29690614, 2018). "In particular are cytokines such as IL-4 and GM-CSF and costimulatory molecule CD80, which stimulate APCs to increase the expression of tumor antigens." (PMID 29662489, 2018). "Phenotype analysis determined that once the cells derived from CCR2+HSCs reach intracranial tumor after intravenous injection, they upregulate markers associated with antigen presenting cells, including CD11c, MHC-II, and CD80." (PMID 30333482, 2018). "First, since soluble CD80 is known to promote tumor rejection as it provides co-stimulation for T cells, blocking this interaction should suppress rather than promote tumor rejection." (PMID 29472691, 2018). "Elderly tumor-associated CD11c+ cells significantly reduced MHC-II and CD80, with a trend for reduced MHC-I (p = 0.08) relative to their younger counterparts." (PMID 30560130, 2018). "IFN-γ not only favors cancer cell apoptosis but also increases MHC-1 and MHC-2 molecule expression, thus helping the cytotoxic cells to recognize the tumor cells expressing the CD80 marker and target for cytotoxicity." (PMID 29662489, 2018). "LY3300054 is a novel human monoclonal antibody (IgG1, lambda, Fc-null) targeting PD-L1 expressed on tumor cells and tumor-infiltrating immune cells, preventing binding to its T-cell receptors (PD-1 and CD-80)." (PMID 30400822, 2018). "To investigate the localization and function of M1/M2 macrophages in the spleens and tumors of HT29 and CT26 tumor-bearing mice, we stained spleen and tumor sections with M1 and M2 macrophage markers, CD80 and MRC1, respectively." (PMID 29690614, 2018). "GRP78 heterozygous tumors also display a higher level of CD80 single positive cells, indicating an elevated monocyte/activated B-cells infiltrating the tumor." (PMID 29113324, 2017). "Monocytes in tumor-bearing mice were on average less differentiated as judged by the decreased frequency of F4/80+ cells and CD80 expression in CD3-CD19- splenocytes as compared to the respective controls." (PMID 28744322, 2017). "While DCs did migrate in vitro similarly toward SN of mock treated and irradiated tumor cells, in particular SN of irradiated tumor cells induced an increased expression of the activation markers CD80 and CD86 on DCs." (PMID 28337197, 2017).
tumor (continued). "That is, we found that patients with a tumor microenvironment (TME) rich in CD163+Foxp3+ CD80+ experience a higher rate of cancer recurrence compared to patients with TME low in CD163+Foxp3+ CD80+." (PMID 28947958, 2017). "These molecules are expressed on activated T cells, but when they adhere to ligands either on APC (CTLA-4 binding to CD80/CD86) or tumor cells (PD-1 binding to PD-L1), they tend to suppress the antitumor response." (PMID 28878676, 2017). "If a tumor cell that expresses PD-L1 on its surface encounters antitumor CD8+ effector T cells that expresses PD-1 or CD80, then the tumor cell will initiate signaling downstream of PD-1 and CD80." (PMID 28848559, 2017). "Activated MDSCs isolated from tumor bearing mice and from cancer patients show a significantly enhanced expression of CD80, defining CD80 as activation marker for MDSCs." (PMID 28835242, 2017). "In this study, Treg cells that had encountered the tumor antigen in draining lymph nodes subsequently interacted with DCs within the tumor leading to the downregulation of costimulatory molecules CD80/86 on DC surface." (PMID 28382036, 2017). "Another interacting molecule such as B7-1 (CD80), a protein expressed on activated T cells and APCs, interacts with the PD-L1 of tumor cells causing the negative regulation of effector T-cell activation." (PMID 28878676, 2017). "PD-L1 overexpression is also found on many tumor types and mediates an immunosuppressive function through its interaction with PD-1 and other proteins, including CD80 (B7.1)." (PMID 27145284, 2016). "Recent progresses in tumor immunology identified a series of costimulatory molecules such as B7 homolog 1 (B7-H1, PD-L1, CD80), B7-H2 (CD 86), B7-H3 (CD 276), and B7-H4 (B7x, B7S1)." (PMID 27835582, 2016). "Whereas in vitro the additional presence of CD80 led to a better immune response, this setting was less efficient in controlling tumor growth and spreading in vivo." (PMID 27437103, 2016). "Blockade of MHC class I, CD40 or CD80 resulted in a substantial reduction of anti-tumor cytotoxicity against target tumor cells, although it was dependent on cell type." (PMID 27671170, 2016). "Before loading with tumour lysate, DCs were characterized by flow cytometry to analyse the expression of MHC class I and II molecules, costimulatory molecules (CD86, CD80, CD40), and markers associated with maturation (CD83, CCR7, PD-L1)." (PMID 26795765, 2016). "Oncogenic insults inducing CD80 expression seem then to be able to modulate the anti-tumor immune response." (PMID 27377375, 2016). "In particular, CD80 or MHC class I blockade strongly inhibited the anti-tumor cytotoxicity induced by combination treatment of decitabine with IR against all target tumor cells." (PMID 27671170, 2016). "The mRNA levels of PD-L1 and CD80 were significantly increased following treatment with cisplatin alone in ID8 tumours." (PMID 27147225, 2016). "Blocking of the MHC class I and CD80 resulted in a substantial reduction of IFN-γ production against all target tumor cells, but CD40 blockade significantly reduced only in A549 tumor cells." (PMID 27671170, 2016). "The spleens obtained from tumor-bearing mice also had up-regulation of many dendritic cell and macrophage maturation markers such as CD80, CD86, F4/80 and MHCII." (PMID 27246354, 2016). "Specifically, genetic variation in CD80 was associated with poorer survival of endometrioid cases and with increased tumor CD80 expression." (PMID 27533245, 2016). "A prominent contraction of the CD80+ population within grMDSCs was observed upon vaccination for subcutaneous tumours." (PMID 26931556, 2016). "LPS-activated CD14+ CD11c+ human phagocytes expressed significantly higher levels of the inflammatory macrophage/DC marker CD80 in tumor spheroids, which again further increased upon addition of IFN-γ." (PMID 25871398, 2015).
tumor (continued). "Second-generation CARs that express CD28-containing costimulation in the CD19+CD80/CD86-ALL SCID-beige tumor model showed superior in vivo tumor activity and T cell function." (PMID 26377367, 2015). "To determine if the differences between 19-28z+ T cells and CD80-costimulated 19z1+ T cells observed in vitro would have an impact in a therapeutic setting, we compared their anti-tumor activity in a newly established systemic tumor model." (PMID 26110267, 2015). "As markers of such an immune response we analyzed shrinkage of tumor spheroids, CD80/CD86 expression on antigen-presenting cells (APCs), and granzyme B (GrB) expression by CTLs." (PMID 25871398, 2015). "Along these lines, blocking CD80 reduced the number of GrBhi CTLs and prevented tumor spheroid killing." (PMID 25871398, 2015). "APCs presenting a self-tumor antigen in the presence of a costimulatory signal in the form of upregulated CD80 or CD86 (normally triggered by a microbial stimulus) induce either anergy, deletion of tumor-specific T cells, or expansion of T-regulatory cells." (PMID 26221602, 2015). "CD80 expression in tumor-spheroid infiltrating mPGES-1−/− macrophages translated into antigen-specific cytotoxic T cell activation." (PMID 25871398, 2015). "Modulation of costimulatory molecule expression by PGE2 requires the tumor scenario as CD80 expression of mPGES-1−/− BMDMs was similar to WT BMDMs in monocultures." (PMID 25871398, 2015). "To further probe antigen-presenting cells (APCs) in the tumor, we choose antibody against CD80, a marker for matured APCs, for IHC analysis." (PMID 26107716, 2015). "Upon initial activation by antigen-presenting cells (APCs), tumor-specific T cells receive essential co-stimulation through binding of CD28 to CD80/86 on activated APCs." (PMID 24855562, 2014). "DAC-induced CTL response appeared to be elicited by the induction of CD80 expression on tumor cells." (PMID 23671644, 2013). "In the tumor microenvironment, the promoter region of CD80 gene in cancer cells is highly methylated, therefore CD80 is not expressed." (PMID 23671644, 2013). "There was an enhanced expression of CD40 and CD80 in the tumor lysate (TL)-pulsed DC that was co-cultured with TRF as compared to DC alone." (PMID 24069344, 2013). "Classic tumor immunology studies have revealed that ectopic expression of CD80 on tumor cells has potent effects on the induction of anti-tumor immune responses, mainly anti-tumor CTL response and sometimes NK response." (PMID 23671644, 2013). "Our study shows that TRF increased the expression of CD40 and CD80 in the DC-pulsed with tumor lysate in a dose-dependent manner." (PMID 24069344, 2013). "Second, in this study we found that in DAC-treated tumor bearing animals, tumor cells strongly up-regulated CD80." (PMID 23671644, 2013). "To further understand the impacts of DAC-induced tumor cell expression of CD80 on T cell activation and effector functions, we performed mixed lymphocyte culture and CD80 blockade experiments." (PMID 23671644, 2013). "Cryosurgery of primary tumor in mice has demonstrated accumulation of CD80+ CD11c+ DCs in the LNs as well as induction of IFN-γ+ CD8(+) T cells in the tumor-DLN but only when cryosurgery was combined with intratumoral CpG administration." (PMID 23133545, 2012). "One approach is to include lymphokines (GM-CSF, IL-12, IL-15) or include tumour cell expression of membrane bound molecules (CD80, CD86)." (PMID 23046944, 2012). "Tumor cells can escape the immune system by overexpressing molecules of the B7 family, e.g. B7-H1 (PD-L1 or CD86), which suppresses the anti-tumor T-cell responses through binding to the PD-1 receptor, and similarly for B7.1 (CD80), through binding to CTLA-4." (PMID 21884581, 2011).
tumor (continued). "One such mechanism is represented by tumor-induced overexpression of CD80 (B7-1) on the surface of MDSCs, to which the inhibitory CTLA-4 (CD152) molecule expressed on CD4+CD25+ T cells binds with high affinity." (PMID 22190971, 2011). "The A549 tumour cell line was only used in these experiments as they exhibited greatest change in CD80/83/86 expression, and so would be most likely to activate T cells." (PMID 19997099, 2010). "DCs maturation was evaluated by IL-12/IL-10 production and CD80/CD86 expression after co-culture with tumor cells treated with different HIFU." (PMID 20105334, 2010). "The immunization of animals with specific tumor cells transduced to express HLA class II and the costimulatory molecules CD80/CD86 have been shown to halt tumor progression and establish an immune memory against the specific tumor." (PMID 20016802, 2009). "This indicates that DC that acquired OVA-Alexa, as an indicator of tumour-debris, preferentially upregulate CD80, whereas this effect is further enhanced by ablation." (PMID 16953240, 2006). "OVA-Alexa(+) DC showed a three-fold increase in CD80 expression relative to OVA-Alexa(−) DC in tumour-bearing and naïve mice (MFI's 987, 318 and 310, respectively)." (PMID 16953240, 2006). "They code for co-stimulatory molecules known to enhance tumor cell immunogenicity: CD80, a member of the B7 family and CD70, a member of the TNF family." (PMID 15279677, 2004). "These tumor cells would therefore be genetically modified to express two co-stimulatory molecules, CD70 and CD80, which are known to induce an anti-tumor response in syngeneic mice." (PMID 15279677, 2004). "Notably, TNF-α producing activated dendritic cells (CD80+) correlated with enhanced tumor suppression." (PMID 41522339, 2026). "Western blot analyses of tumor tissues revealed that BPA reduced the expression of marker proteins associated with M2-TAMs and Tregs, while increasing the expression of the immune-stimulatory markers CD80, GITR and CD4." (PMID 41597201, 2026). "Firstly, it promotes the STAT3 signaling pathway and macrophage M2-type activation, which are linked to the inhibition of the tumor immune response; secondly, it lowers the expression of MHC II and CD80 to impact macrophage antigen-presenting ability and T cell activation." (PMID 40032844, 2025). "We investigated macrophage activation in spleen and tumor tissue via CD80 and CD86 expression." (PMID 41583493, 2025). "In contrast, the regulatory impact of tumor cells, either alone or depending on their treatment, on M2-like macrophage activation, which most likely mimics TAMs, was relatively small, with a significant induction of CD80." (PMID 40724825, 2025). "Treatment with anti-CD80/CD86 blocked this radiation-mediated increase in Treg in the tumor." (PMID 41417245, 2025). "Additionally, flow cytometric analysis of mature dendritic cells (identified as CD80+/CD86+ within the CD11c+ cells) from tumor-draining lymph nodes revealed that these DCs effectively home to the tumor-draining lymph nodes and undergo maturation." (PMID 40761260, 2025). "As Treg are the dominant CTLA4-expressing CD4 T cell that could productively interact with MHCII and CD80/86 expressing macrophages, it is notable that these cells have been shown to expand in proportion in the tumor at later timepoints following RT." (PMID 41417245, 2025). "It was recently demonstrated that in CCH, tumor cells express both markers and that a decrease in CD80 may have an impact on regression." (PMID 40271486, 2025). "Another modified adenovirus, LOAd 703, which encodes CD40L and 4-1BBL, has been shown to enhance cytotoxic T cell activity and inhibit tumor progression in a multiple myeloma xenograft model; it also increases tumor immunogenicity by upregulating costimulatory markers CD80 and CD86." (PMID 41294877, 2025). "Finally, we demonstrated that blockade of CD80 and CD86 improved the response to radiation, associated with decreased Treg in the tumor." (PMID 41417245, 2025).